C3 (complement C3)
Diseases named in the same sentence as C3 in open-access papers (continued):
Sharing a sentence is not in itself a finding about the gene and the disease.
tumor (continued). "Irradiation treatment could trigger the strong complement activation in the tumor-bearing mice, probably resulting from the irradiation-induced cell death and the increased C3 expression." (PMID 30166523, 2018). "The most downregulated protein (RPL29, log2FC –5.2), is a member of the 60S ribosome which indicates that C3 may be acting to modify translational pathways, consistent with a hypothesis that C3 is exerting anti-tumor effects through 37 LR." (PMID 29464047, 2018). "Interestingly, C3 expression in tumor cells is transcriptionally regulated by twist basic helix–loop–helix transcription factor 1 (TWIST1), which binds to the C3 promoter and enhances its expression." (PMID 30061895, 2018). "Moreover, postoperative C3 depletion and advanced tumor stage were independent predictive factors of poor prognosis." (PMID 29062836, 2017). "In addition, levels of hepsin protein correlated positively with C3 expression in human non-tumor liver tissues." (PMID 26760961, 2016). "Similarly, C3 was found in the cytoplasm of the epithelial cells, but the intensity was significantly higher in tumor cells compared to normal keratinocytes (Mann Whitney U test, p = 0.016)." (PMID 26540631, 2015). "Furthermore, It has been found in number of cancer models that tumor inflammatory microenvironment constitutes complement activated fragments C3, C4, and C5, Clq, and MAC, high levels of IL-6 and TGF-β." (PMID 26198107, 2015). "Because C3f, as a fragment of complement C3, exists throughout the blood circulation and within tumor tissues, it remains unclear whether other protease(s) among possibly hundreds in biofluids, in addition to MMP-9, could also specifically cleave C3f4." (PMID 25788424, 2015). "Another study indicated that the tumor cells themselves could also directly activate complement C3, resulting in activation of the complement alternative pathway to kill tumor cells." (PMID 25017204, 2014). "Complement C3 may be used as a marker for the diagnosis of early-stage PC, while complement C4b1 and apoE are closely correlated with tumor development, reflecting the biological behavior of PC, and thus may be used as diagnostic markers of advanced PC." (PMID 23946775, 2013). "However, so far these complement-deficient mouse strains are derived from immunocompetent mice, for example, C3-/-C4-/- was from C57Bl/6 background, in which human tumours cannot be generated." (PMID 20939894, 2010). "However, recent murine experiments have also indicated that the activation of C5a, which is activated by C3, leads to immunosuppression of tumour-infiltrating monocytes." (PMID 20877360, 2010). "Therefore, C3 split product deposition (measured as C3b) was analysed on MCP and/or DAF-deficient tumor cells following complement activation." (PMID 19878546, 2009). "For example, aberrant C5a and C3 expression can upregulate pro-metastatic transcription factor and matrix metalloproteinase expression, promoting epithelial-mesenchymal transitions and extracellular matrix reorganisation to facilitate tumour cell dissemination." (PMID 39765018, 2025). "Furthermore, cytokines secreted by TH2 cells, including IL-4 and IL-13, stimulate lung mesenchymal stromal cells to upregulate C3 expression, which promotes neutrophil recruitment and the formation of extracellular traps, ultimately contributing to tumor metastasis." (PMID 40260250, 2025). "Additionally, C3 modulates the polarisation of TAMs, suppressing anti‐tumour immune responses." (PMID 40847563, 2025). "However, conspicuous is the fact that the role of the axis in oncogenesis is rather ambiguous, since a number of studies have demonstrated that tumor grows under C3/C5 activation conditions through recruitment and activation of myeloid suppressor cells in tumors." (PMID 39896931, 2024).
tumor (continued). "In addition, M2 macrophages synthesize C1q, a complement component that binds to the Fc portion of anti-tumor antibodies and triggers the classical component cascade in the presence of complement components such as C1r, C1s, C4, C2, C3 and C5 produced by tumor cells." (PMID 37622111, 2023). "The gene sequence of the C3 probe and ovalbumin (OVA) were connected using internal ribosome entry site (IRES), leading to each tumor cell simultaneously expressing the C3 probe and OVA protein, which could be recognized specifically by OT-I CTLs and characterize caspase-3 activity." (PMID 33391470, 2021). "Moreover, in silico analysis of tumor immune cell infiltration suggested the change of C3 expression could affect tumor microenvironment." (PMID 34722636, 2021). "To explore the specific killing of tumor cells by CTLs in vivo, we choose mCerulean3 and cpVenus fluorescent proteins, variants of cyan and yellow fluorescent proteins 36, 37, as a FRET pair to construct a new genetic encoded probe for detecting caspase-3 activity, denoted as C3." (PMID 33391470, 2021). "Evidence suggests that C3 deposits may activate JAK2/STAT3 to enhance tumour growth." (PMID 33802004, 2021). "Interestingly, C1q-deficient mice, which are unable to activate the classical pathway, also showed a reduced tumor growth, but the degree of protection was less pronounced than in the C3−/− mice, indicating that the activation of C3 was only partially mediated through the classical pathway." (PMID 32682912, 2021). "In addition, it had been reported that tumor cell–derived C3 could regulated TAMs through C3a-C3aR-PI3Kγ pathway to suppress the antitumor immunity." (PMID 34266404, 2021). "In a model of metastatic breast cancer, the deposition of C3 cleavage fragments, indicating complement activation, was found in the lungs starting from day 4 after injecting tumor cells into the mammary fat pad and before the arrival of tumor cells to this organ." (PMID 33271774, 2020). "Therefore, we hypothesized that aggregated neutrophils, which can form NETs primed by G-CSF, contributed to the increased motility of C3, thus promoting the dissemination of tumor cells and aggravating the illness." (PMID 30778902, 2019). "However, beyond empirical speculation, we found that the level of complement C3 correlated positively with poor differentiation of tumor cells and an unfavorable prognosis of HCC." (PMID 31136099, 2019). "Moreover, immunofluorescence and immunoblotting on the final day of treatment showed that the levels of TRIB3, LC3II and cleaved C3 were enhanced in these tumours when they had been treated with GA, supporting the idea that this compound also induces autophagy-mediated cell death in vivo." (PMID 31578236, 2019). "As a combined abnormal inflammatory response with abnormal CH50 and C3 serum levels, without ocular inflammation or neoplastic diseases were documented in the first study, here we focused on risk alleles for AMD that involve different complement factors of the alternative complement pathway." (PMID 29717154, 2018). "The 8 SNPs (CD3EAP rs967591, TNFRSF10B rs1047266, AKT1 rs3803300, C3 rs2287845, HOMER2 rs1256428, GNB2L1 rs3756585, ADAMTSL3 rs11259927, and CD3D rs3181259) were found to be significantly associated with OS and/or DFS when adjusted for age, gender, smoking status, tumor histology, pathologic stage." (PMID 26462029, 2015). "When IDO is blocked and tumors are further exposed to radiation, these may act together to sensitize the chemotherapy-induced perivascular cuff to allow innate inflammation, endothelial cell activation, widespread complement C3 deposition, and microangiopathic tumor destruction." (PMID 25054064, 2014).
tumor (continued). "Thus, host IDO activity regulated complement deposition in glioblastoma tumors after chemo-radiation therapy, and complement deposition was highly selective and confined to the tumor itself.Image analysis software was used to quantitate photomicrographs of tumors stained for complement C3." (PMID 25054064, 2014). "Thus, C3 deficiency did not alter the underlying growth kinetics of the tumor, or the baseline response to chemo-radiation therapy." (PMID 25054064, 2014). "For example, a recent report indicates that hypoxia-dependent increases in C3 and C3aR expression in GBM cell lines enhance tumour growth via crosstalk with macrophages." (PMID 40695778, 2025). "In contrast, ADAMDEC1+ Fibro, C3+ Fibro, CFD+ Fibro, DPT+ Fibro, Proliferating Fibro, and Myo Fibro were present in both tumor and normal tissues and were therefore classified under the Fibro group." (PMID 41031085, 2025). "In this study, we demonstrate that C3, C3AR1, and C5AR1 are robustly expressed in GBM cells, indicating potential tumor cell-specific functions of these complement components." (PMID 40843669, 2025). "Our results demonstrate the upregulation of C1R, C1S, C3, IGHM and CFB in poorly differentiated tumours, suggesting activation through the classical pathway." (PMID 40847563, 2025). "It was not until the groups were separated by sex that it was apparent that there were significant sex-based differences in tumor growth when both MUC1 antigen and TLR agonists were combined into a single set of C3-liposomes." (PMID 40284463, 2025). "Moreover, cancer.cell.2, cancer-associated C3+ fibroblasts (CAF_C3), and Fibrocyte_CD34, which are prone to accumulate in the metastatic site and post-NACT group, harbored poor clinical outcome, reflected in the immune exclusion and tumor progression signaling." (PMID 40725006, 2025). "Immunohistochemistry assay of the xenograft tumor sections indicated that COTI-2 treatment significantly decreased the expression of Ki-67 and increased the expression of Cleaved C3." (PMID 39906622, 2025). "Concurrently, C3 cleavage fragments stimulate the JAK2/STAT3 and ERK pathways, driving cellular reprogramming that promotes tumor progression." (PMID 40370471, 2025). "To understand the role of C3 and complement in the tumor microenvironment, we returned to stain the murine GBMs for C3, GFAP, Olig2, and Nestin to highlight perivascular tumor areas." (PMID 39172519, 2024). "This study established a seven-gene profile (FGG, C3, FGA, JUN, CST3, CPSF4, and HIST1H2BH) prognostic stratification system demonstrated in LUSC based on Tumor Progression, Immune Infiltration, and Stem Index." (PMID 37841237, 2023). "The mRNA expression levels of three key genes (USP34, C3 and MGP) based on TCGA tumor data were also determined, and the USP34 gene was highly expressed in the cancer cell lines included in the T-LBL and T-ALL datasets according to CCLE analysis." (PMID 37664545, 2023). "Previous studies have shown that a high expression of C3, TIMP-1, and AHSG genes in tumors can promote tumor cell proliferation and tumor deterioration." (PMID 35935258, 2022). "In addition, tumor cells could release (pro)cathepsin L to cleave C3." (PMID 36294966, 2022). "Altogether, these data indicate a role for the complement system, in particular for C3 and C3a, in making the TME beneficial to tumor growth, proliferation, and angiogenesis." (PMID 35669782, 2022). "On the contrary, both perforin- and C3-mediated mechanisms, including ADCC, CDCC, and antibody-dependent cellular phagocytosis (ADCP), provide partial but significant support to the anti-tumor effect exerted by anti-Her2 antibodies." (PMID 35203439, 2022). "C3, C3AR1, and C5 participate in the genesis and development of multiple tumor types, while their effects on ccRCC remain obscure." (PMID 34688260, 2021).
tumor (continued). "Although accumulating evidence agrees on the pro-tumoral role of C5, C3, C3AR1, and C5AR1, the immune infiltration is largely controlled by the properties of the tumor cells themselves." (PMID 34439277, 2021). "C3, APP, GAL, and C3AR1 have also been shown to be involved in the regulation of cancer cell metastasis and tumor invasion in multiple cancers." (PMID 34239596, 2021). "High C3 levels are indicative of good prognosis in NSCLC, with greater numbers of infiltrating CD4+ and CD8+ T cells reported in tumours with increased C3 expression." (PMID 33802004, 2021). "The findings indicated that both IHC C3 score (AUC = 0.651) and serum CEA level (AUC = 0.646) were valuable in predicting oncologic outcome, but inferior to pathological tumor stage (AUC = 0.842)." (PMID 31928530, 2020). "ANKRD1 was abundant in the tumour centre, while AMOTL2 and AXL were higher at periphery, where C3-positive microglia were also observed." (PMID 32404936, 2020). "However, C3 might play a double-edged role in the tumor microenvironment." (PMID 31928530, 2020). "In particular, the level of complement C3 with Man5, Man6 or Man7 glycoforms at Asn85 was found to be correlated with HCC tumor grade, even more than α-fetoprotein (a well-known HCC biomarker)." (PMID 33198323, 2020). "We found commonly deregulated factors in LECs in both metastatic tumor cell models, namely a strong up-regulation of E-selectin, cytokine CCL7, and complement component 3 (C3)." (PMID 31963450, 2020). "In the context of adoptive T-cell transfer, the capacity of tumor-reactive CD4+ and CD8+ T cells to infiltrate tumors requires the local production of C3, complement activation and release of C5a." (PMID 31031765, 2019). "Stepwise Cox regression analyses revealed that tumor stage, AST, complement C3 with Man5 glycoform, and complement C3 with hybrid glycoform were independent factors for the recurrent HCC." (PMID 31136099, 2019). "Further, C3 and other complement components were significantly increased by metronomic CPA treatment in both tumor models and likely contribute to the observed innate immune activation and clearance of dying tumor cells." (PMID 25952672, 2015). "It has been shown previously that complement components such as C1q, C3, C3a, C4, C5, and the membrane attack complex (MAC) are deposited in the inflammatory tumor microenvironment." (PMID 24455486, 2014). "For example, several associations between neoplasm-related ADRs and known tumor suppressor (Syk) and tumor invasiveness marker (MMP-1 and C3) proteins are found." (PMID 25191698, 2014). "It has been demonstrated previously that complement components such as C1q, C3, C3a, C4, C5 and the MAC were deposited in the inflammatory tumor microenvironment." (PMID 24205138, 2013). "Our group previously demonstrated that C3 (OPSS)-liposomes enhance antigen uptake by antigen-presenting cells (APCs) via the complement C3 pathway and, when combined with toll-like receptor (TLR) agonists, reduce tumor growth in murine cancer models." (PMID 40284463, 2025). "In contrast, no notable changes in C3 expression level were observed in other types of cells including tumor cells, immune cells and endothelial cells." (PMID 38798691, 2024). "Moreover, C3, C3a-C3aR axis, C5a/C5aR1 axis and other complement pathways can also regulate immune cell response and TIME, and participate in tumor progression in CRC." (PMID 38918278, 2024). "Accordingly, we found that CXCL2+ CAFs may secrete complement C3 to interact with C1Q+ TAMs, mainly targeting the pro‐angiogenic gene VEGFA to maintain their M2‐like phenotype in chemoresistant tumours." (PMID 39422697, 2024). "However, since MHC-II expression in tumor cells can also be induced by IFN-γ, there is a possibility that C3 represents a byproduct of a favorable immune microenvironment." (PMID 39664386, 2024). "Tumors were stained for C3, GFAP as an astrocytic marker, and Olig2 for the bulk of tumor cells." (PMID 39172519, 2024).
tumor (continued). "In the present study, C1q, C3 and C9 were detected by IF only in the tumor mass of animals treated with AT101 and not with non-specific IgM, that have no specificity for tumor cells." (PMID 38017492, 2023). "In contrast, expression of C3, SFRP2, STAT3, IL-6 and THY1 was increased in tumor-distal stroma." (PMID 37350578, 2023). "We observed that MFAP5 + fibroblasts were the main senders that could release complement C3 to interact with the receptors ITGAM/ITGB2, ITGAX/ITGB2, and C3AR1 of C1QC + macrophages in tumor tissues, thus activating the complement system." (PMID 37344903, 2023). "Interestingly, this study also confirmed a significant reduction of macrophages recruited into the tumor bed of C3 and C3aR KO compared to WT MN/MCA1 tumor-bearing mice." (PMID 37174113, 2023). "Host cells in the tumor microenvironment, including immune and non-immune cells, such as fibroblasts, can express and secrete C3 and other complement proteins." (PMID 35860237, 2022). "On the other hand, delayed tumor growth observed in CreERT2 mice is supported by reduced proliferation (Ki67+ cells) and vascularization (CD31+ area), as well as increased apoptosis (C3+ cells)." (PMID 35688943, 2022). "Using in vitro co-cultures of breast and prostate cancer cells with lymphatic endothelial cells (LEC), Oliveira-Ferrer demonstrated tumor-dependent induction of C3, CFB and C1q secretion as well as that chemokine upregulation (CCL7, CXCL6, CXCL1) by the LECs promotes tumor metastasis." (PMID 35860237, 2022). "Tumor progression can be prevented when MBL or C3 is absent in tumor cells in the extratumoral region or when c3ar is knocked out." (PMID 36466871, 2022). "In the tumor microenvironment, T-cell trafficking, and tissue infiltration of CD8-positive T cells via endothelial cells require complement activation, local production of C3 and C5a." (PMID 35755033, 2022). "The tumor immune estimation resource (TIMER) platform was applied to explore the correlation between infiltration levels of immune cells and the expression of four prognosis-related genes (including NR6A1, CXCL5, TGFB1, and C3)." (PMID 36071851, 2022). "The result showed that the lower mRNA expressions of C3, C5, CFB, and CLU were correlated with more advanced cancer stage, while the lower mRNA expressions of C1S, C8B, CFI, MBL2, and C4BPA were correlated with higher tumor grade in HCC patients." (PMID 34813686, 2022). "R848 delivered by complement C3-targeted liposomes triggered various signal cascades to increase the expression of cytokines and factors (such as TNF-α, IL-1β, IL-6 and IL-12), leading to the delay of tumor growth in 4T1 tumor-bearing mice." (PMID 35413927, 2022). "Tumor sections were obtained from Hh-type MB patients and stained for C3 and C3a proteins, and it was found that both C3 and C3a were abundantly present in the tumor area, whereas they were not detectable in the tumor-adjacent normal tissue area." (PMID 35725556, 2022). "While in all pVAX-vaccinated mice TUBO cells gave rise to a palpable growing tumor, 100% of RHuT-vaccinated animals, regardless of the presence or absence of perforin, C1qA or C3 molecules, were protected." (PMID 35203439, 2022). "In addition to C3 and CFH, cancer cells have been shown to produce and secrete other complement proteins that suppress anti-tumor immunity." (PMID 35860237, 2022). "In fact, these findings are in accordance with previous reports of tumor cells or recruited immune cells like TMAs or CAFs, showing higher expression and production of different complement factors including not only MBL but also C1q and C3 (see Section 5.1)." (PMID 36547187, 2022). "Immune infiltrates corresponding to human tumor suppression and promotion, respectively, namely C1 (wound healing), C2 (INF-g dominant), C3 (inflammatory), and C4 (lymphocyte depleted), were applied to understand the connection between immune components and the risk signature." (PMID 34721986, 2021).